IGHJ2 (immunoglobulin heavy joining 2)
Synonyms: JH2
Gene: Immunoglobulin joining (J) gene on chromosome 14 (105,865,199 to 105,865,250, reverse strand). Ensembl gene ENSG00000211904.
Diseases named in the same sentence as IGHJ2 in open-access papers:
IGHJ2 is named in the same sentence as 1 disease in open-access papers, as found by Europe PMC text mining. Sharing a sentence is not in itself a finding about the gene and the disease.
IGHJ2 shares sentences with these, for which no sentence is quoted: cancer (1 paper).